USH2A (usherin)
Diseases named in the same sentence as USH2A in open-access papers (continued):
Sharing a sentence is not in itself a finding about the gene and the disease.
Usher syndrome (continued). "In addition, half of the cases with Usher syndrome caused by USH2A mutations had two different premature stop codon formations in each allele (trans-compound heterozygous)." (PMID 30374144, 2018). "The USH2A gene mutations have been reported in the Usher syndrome and non-syndromic RP." (PMID 28838317, 2017). "In addition to these six pathways, frequent non-silent sequence mutations were found in FCGBP (immunoglobulin Fc gamma-binding protein; n=4) and USH2A (mutated in Usher syndrome and retinitis pigmentosa; n=4)." (PMID 25790293, 2015). "USH2A mutation can cause Usher syndrome that results in hearing loss and retinitis pigmentosa." (PMID 25353171, 2014). "An additional 22 syndromic deafness genes were also included in the screening in case that any additional symptoms of syndromic deafness were either overlooked or absent during the clinical evaluation (see discussion below on USH2A mutations and Usher Syndrome type 2A)." (PMID 23767834, 2013). "This is the first time that a duplication in USH2A has been reported as a cause of Usher syndrome." (PMID 23924366, 2013). "CERKL mutations have been previously reported as significant causes of autosomal recessive RP in Middle Eastern populations, while USH2A represents one of the most common causes of Usher syndrome worldwide, suggesting that this gene may be particularly important in the Turkish RP population." (PMID 41562913, 2026). "Usherin is the most common causative protein associated with autosomal recessive retinitis pigmentosa (RP) and Usher syndrome (USH), which are characterized by retinal degeneration alone and in combination with hearing loss, respectively." (PMID 32637036, 2020). "Mutations in the Usher syndrome 2A (USH2A) gene give rise to two distinct phenotypes, USH type II (USH II) and non-syndromic RP, which account for 55–90% and 12–25% of cases, respectively." (PMID 31904091, 2020). "Mutations in USH2A are the major cause of Usher syndrome (USH) and autosomal recessive nonsyndromic retinitis pigmentosa (RP), which account for 30–70% and ~8% of the two diseases, respectively." (PMID 32637036, 2020). "Interestingly, these same USH2A variants are also identified in another family with vision loss where subsequent clinical follow-up confirmed pre-existing hearing loss since early childhood, eventually resulting in a reassigned diagnosis of Usher syndrome." (PMID 31046701, 2019). "Mutations in USH2A are the most common cause in autosomal recessive RP, but they can also result in the human Usher syndrome (USH)." (PMID 31842393, 2019). "Finally, by examining a cohort of patients with Usher syndrome, a genetically well-characterized deaf-blindness syndrome, we could show that recessive pathogenic mutations in the USH2A gene influence touch acuity." (PMID 22563300, 2012). "We next sought to develop a mouse model of Usher syndrome containing the Ush2a c.11840 G > A (p.W3947X) premature termination codon for testing RNA editing strategies in vivo." (PMID 39922978, 2025). "For larger genes such as ABCA4 (Stargardt disease) and USH2A (Usher syndrome type 2A), dual-AAV systems have been developed to overcome size limitations, while CRISPR/Cas9-based genome editing has been explored for precise mutation correction." (PMID 40143072, 2025). "Targeted exome sequencing identified four distinct genotypes and likely pathogenic sequence variants in cell lines derived from clinically diagnosed Usher syndrome patients: MY07A, CDH23, USH2A, and CLRN1." (PMID 39337481, 2024). "Whilst suitable for a number of ciliopathy-related genes, such as RPGR (3.5 kb), many genes are beyond this capacity, including CEP290 (7.4 kb) and several of the Usher-syndrome-associated genes (MYO7A: 6.6 kb, CDH23: 10 kb, ADGRV1: 18.9 kb, USH2A: 15.6 kb)." (PMID 38474133, 2024). "USH2A variants (USH2A, OMIM #608400: autosomal recessive) can cause a form of RP associated with neurosensory hearing loss (Usher syndrome) or isolated RP." (PMID 38610844, 2024).
Usher syndrome (continued). "Usherin, encoded by the fly gene CG5921, is implicated in usher syndrome type 1, an autosomal recessive sensory disorder that causes deafness, blindness, and vestibular defects." (PMID 38412189, 2024). "Five genes (USH2A, USH1G, USH1C, MYO7A, and PCDH15) were associated with Usher syndrome from Africa." (PMID 34609590, 2022). "Mutations in USH2A and MYO7A were responsible for two-thirds of solved cases (48% and 20%, respectively), in line with the high prevalence of Usher syndrome patients (78.6% of syndromic cases)." (PMID 36460718, 2022). "Mutations in the USH2A gene cause Usher Syndrome type II (USH2), which is the most common subtype of Usher Syndrome and the focus of this review." (PMID 36232969, 2022). "Usher syndrome, most frequently due to biallelic variants in MYO7A (USH1B in 16 probands), USH2A (17 probands), and ADGRV1 (USH2C in 7 probands), was diagnosed in 44 of 59 (75%) unrelated probands." (PMID 34148116, 2022). "Some PSGs that form hair bundle links are also implicated in vision; for example, PCDH15, USH2A, and ADGRV1 are all involved in Usher syndrome, congenital deafness due to stereocilia disorganization with associated progressive retinitis pigmentosa." (PMID 34137817, 2021). "Alterations in USH2A are responsible for Usher syndrome, which is the most common syndromic RP with sensorineural hearing loss." (PMID 33105608, 2020). "The remaining three solved cases suffered from Usher syndrome due to putative pathogenic variants in ADGRV1, CDH23 and USH2A, one family for each gene." (PMID 33297549, 2020). "Ush2a-knockout in mice and in zebrafish recapitulated a phenotype of human Usher syndrome with retinal degeneration and hearing problems." (PMID 33105608, 2020). "To date, 10 causative genes have been identified for Usher syndrome, with MYO7A accounting for >50% of type 1 and USH2A contributing to approximately 80% of type 2 Usher syndrome." (PMID 32995707, 2020). "Usher syndrome is classified into three types, type I, II and III, and causal genes of type II include USH2A, ADGRV1, and WHRN (DFNB31)." (PMID 33105608, 2020). "The proteins encoded by these mutant genes, whirlin and myosin VIIA, are among several Usher syndrome proteins found to interact with usherin at the mouse periciliary membrane complex." (PMID 31998945, 2020). "From the arRP patient cohort, 6 patients presented with syndromic disease: 2 with Usher syndrome type 1 (caused by MYO7A) and 4 with Usher syndrome type 2 (3 with disease caused by USH2A and 1 with GPR98)." (PMID 31341231, 2019). "Our results revealed six novel mutations in the USH2A gene in a Chinese population, which is beneficial for the clinical use of genetic testing of USH2A in patients with autosomal-recessive or sporadic RP and Usher syndrome." (PMID 29899460, 2018). "The present study sought to elucidate differences in cone function between Usher syndrome and NSRP due to mutations in the same USH2A gene." (PMID 28894305, 2017). "The largest homozygous region was about 42 Mb and contained three IRD-associated genes: CRB1, RD3 (retinal degeneration 3; OMIM# 180040), and USH2A (Usher syndrome type 2A; OMIM# 608400)." (PMID 28460491, 2017). "The present study focused specifically on Usher syndrome and recessive NSRP due to mutations in USH2A, and is first to elucidate differences in cone function between these groups." (PMID 28894305, 2017). "The structural variants observed using this approach were identified in genes as diverse as the conditions themselves involving gyrate atrophy (OAT), retinitis pigmentosa (USH2A) and Usher syndrome (USH1C)." (PMID 29099798, 2017). "Although mutations in 12 genes have been described to cause Usher syndrome, the most common subtype of Usher syndrome remains USH2 and mutations in USH2A have been identified in the majority of the reported cases." (PMID 25333064, 2014).
Usher syndrome (continued). "Mutations in the USH2A gene are responsible for the majority of USH2 cases and are also responsible for atypical Usher syndrome and recessive non-syndromic RP." (PMID 24086419, 2013). "USH2 accounts for well over one-half of all Usher cases and mutations in the USH2A gene are responsible for the majority of USH2 cases, but also for atypical Usher syndrome and recessive non-syndromic RP." (PMID 24086419, 2013). "Several of the top candidate genes include EEF1A1, ROBO1, PLXNA4, SLIT3, NRP1, and NOTCH2, as well as genes associated with the Usher syndrome, PCDH15 and USH2A, and are plausible candidates contributing to the developmental defects in Gbx2−/− mice." (PMID 23144817, 2012). "In the third set of experiments with a cohort of Usher syndrome patients, we identified a single gene, USH2A or Usherin, mutations in which are associated with poor touch acuity as well as congenital hearing loss and adult onset blindness." (PMID 22563300, 2012). "In all four families, the coding region (exons 2–72), including the intron-exon boundary of the USH2A (Usher syndrome type −2A protein) gene, was screened by PCR and direct DNA sequencing." (PMID 21686329, 2011). "The complete coding region and exon-intron boundaries of Usher syndrome 2A (USH2A) were sequenced with the proband DNA to screen the disease-causing gene mutation." (PMID 20309401, 2010). "Specifically, disease-causing USH2A variants account for up to ∼50% of all Usher syndrome cases, and are also a common cause of isolated non-syndromic retinitis pigmentosa." (PMID 40235854, 2025). "Variants in the USH2A gene have been described in patients with autosomal recessive retinitis pigmentosa (RP) (Retinitis pigmentosa 39, OMIM:613809) and Usher syndrome type 2 (Usher syndrome, type 2A, OMIM:276901)." (PMID 39596236, 2024). "USH2A mutations are a common cause of autosomal recessive retinitis pigmentosa (RP) and Usher syndrome, for which there are currently no approved treatments." (PMID 37337429, 2023). "Potential causative variants were identified in genes associated with nonsyndromic hearing loss (CIB2, COL11A1, ILDR1, MYO15A, TMPRSS3, and WFS1), nonsyndromic hearing loss or Usher syndrome (CDH23, MYO7A, PCDH15, and USH2A), and other syndromic forms of hearing loss (CHD7, OPA1, and SPTLC1)." (PMID 34837038, 2022). "For example, considering patients affected by both ‘Rod-cone dystrophy’ (HP:0000510) and ‘Hearing impairment’ (HP:0000365), the top two genes predicted are USH2A (HGF: 9.53) and ADGRV1 (HGF: 8.31), both known to cause Usher syndrome that affects both visual and hearing systems." (PMID 32271766, 2020). "Previous studies also supported the correlation between the USH2A gene and Usher Syndrome)." (PMID 31699113, 2019). "The genetic diagnosis was made before onset of RP in 10 young patients with apparently isolated hearing impairment: nine with Usher syndrome due to mutations in MYO7A and USH2A, and one with a peroxisome biogenesis disorder (PBD) due to compound heterozygous PEX26 mutations." (PMID 28944237, 2017). "Although many USH2A pathogenic mutations are associated with Usher syndrome, none of the pedigrees which were initially clinically diagnosed with recessive RP showed any other syndromic traits." (PMID 29099798, 2017). "Interestingly, mutations in some genes leading to Usher syndrome can also manifest as nonsyndromic RP (NSRP) in other individuals, with mutations in Usherin 2A (USH2A) being a frequent cause of both." (PMID 28894305, 2017). "Twelve SNPs were associated with factor 2 (LCDA) levels in any race, with only two of them showing more than nominal significance in the validation cohort (rs12129555 just downstream from polymeric immunoglobulin receptor [PIGR] and rs17025690 in Usher syndrome 2A [USH2a])." (PMID 26540294, 2015).
Usher syndrome (continued). "Specifically, we detected pathogenic DNA variants (∼50% novel mutations) in the genes RP1, USH2A, CNGB3, NMNAT1, CHM, and ABCA4, responsible for retinitis pigmentosa, Usher syndrome, achromatopsia, Leber congenital amaurosis, choroideremia, or recessive Stargardt/cone-rod dystrophy cases." (PMID 23940504, 2013). "Because of the late onset of RP (usually postpubertal) in Usher Syndrome type 2A patients, it was not surprising that we identified bi-allelic USH2A mutations in three “non-syndromic” deaf probands, all under 6 years old." (PMID 23767834, 2013). "Control Usher syndrome cohorts lacking demonstrable pathogenic USH2A mutations showed no impairment in touch acuity." (PMID 22563300, 2012). "Usher syndrome is heterogenous, both in terms of clinical presentation and genetic origin, with a number of diverse genes known to carry pathogenic mutations (Type 1: MYO7A, USH1C, PCDH15, CDH23, USH1G, and CIB2; Type 2: USH2A, ADGRV1, and WHRN; Type 3: CLRN1)." (PMID 38474133, 2024). "USH2 is the most common form of USH, and the Usher syndrome type 2A (USH2A) gene is thought to be involved in 74–90% of USH2 cases." (PMID 34376197, 2021). "In summary, due to more detailed phenotypic analysis of the ush2a mutant zebrafish retina, new insights into USH2A-related retinal disease have been gained, including photopigment mislocalization, elevated autophagy and subcellular trafficking defects, in keeping with other models of Usher syndrome." (PMID 31998945, 2020). "In addition to USH2A, mutations in CLRN1 are also known to cause both Usher syndrome and NSRP33." (PMID 28894305, 2017). "Usher syndrome is characterized by specific phenotypic traits that allow a clear clinical characterization in three main forms, being USH II the most frequent type (between half and two thirds of all cases), and USH2A the major causative gene (75–80% of USH II cases)." (PMID 24516651, 2014). "Specifically, we could confirm that missense mutations in USH2A, a gene found to be mutated in patients suffering from the blindness-deafness disease known as Usher syndrome, cause in general retinitis pigmentosa without hearing loss (patient 08–177)." (PMID 23940504, 2013). "However in the absence of a second mutation we cannot be sure that USH2A is definitely the cause of the atypical Usher syndrome in this family." (PMID 23924366, 2013). "USH2A has been shown to be involved in Usher syndrome and in RP without hearing loss." (PMID 21151602, 2010). "Five patients had obtained a molecular genetic diagnosis of Usher syndrome (CDH23, n = 2; PCDH15, n = 1; USH2A, n = 2) from a genetic screen for early sensorineuronal hearing loss." (PMID 39596324, 2024). "At least 9 causative genes have been found and identified to be responsible for Usher syndrome: Five for USH1 (MYO7A, USH1C, CDH23, PCDH15, and USH1G), three for USH2 (USH2A, ADGRV1, and WHRN) and one for USH3 (CLRN1)." (PMID 38984112, 2024). "The discovery of USH2A mutations reveals novel and potentially exploitable mechanistic insights into rMBGroup4, particularly in view of the established role of USH2A defects in other diseases (retinitis pigmentosa [OMIM:613809], Usher syndrome [276901]24)." (PMID 34272868, 2022). "The large cohort reported here illustrates once more the known genetic heterogeneity of Usher syndrome due to MYO7A and USH2A alterations." (PMID 34948090, 2021). "Although Usher syndrome (USH) has traditionally been characterized as a monogenic and genetically heterogeneous disorder, emerging evidence points to digenic inheritance involving interactions between USH genes such as PDZD7/USH2A in mice and humans." (PMID 40360853, 2025). "USH2A and MYO7A were responsible for most type II and type I Usher syndrome cases, respectively." (PMID 38189974, 2024). "We found touch sensitivity to be impaired in a cohort of individuals carrying pathogenic mutations in the USH2A gene (MIM:608400), but not in other cases of Usher syndrome." (PMID 22563300, 2012).
Usher syndrome (continued). "In organoids generated from patients with RP, a mislocalisation of Usherin, and its interacting partner ADGRV1 were observed; however, both proteins appeared to be entirely absent in Usher syndrome patient-derived organoids." (PMID 38474133, 2024).